LDHA (lactate dehydrogenase A)
Diseases named in the same sentence as LDHA in open-access papers (continued):
Sharing a sentence is not in itself a finding about the gene and the disease.
colon adenocarcinoma (10 papers, 2019 to 2026). "Next, we searched the TCGA database and found that the NRF2 (NFE2L2) gene was positively correlated with the Warburg enzymes LDHA, PGK1, and HK2 in colon adenocarcinoma." (PMID 34094899, 2021). "However, the relevance of LDHA in colon adenocarcinoma (COAD) remains unclear." (PMID 34307169, 2021).
diabetes (10 papers, 2015 to 2025). "The aberrant activation of LDHA or SLC16A1 has been observed to cause diabetes-like phenotype or exercise-induced hyperinsulinism (EIHI)." (PMID 35569803, 2023). "Not only in cancer but also in metabolic syndromes including obesity and diabetes, LDHA is now found operating." (PMID 36407005, 2022). "Islets of individuals with diabetes display an increase in the expression of LDHA when compared to controls." (PMID 26770982, 2015). "LDHA is found upregulated in human islets during type 2 diabetes, which was mainly localized in human α-cells, while it is expressed at a very low level in β-cells, indicating a possible role of LDHA in the islet secretory dysfunction and diabetes progression." (PMID 36407005, 2022). "Islets of individuals with diabetes also display an increase in the expression of LDHA." (PMID 26770982, 2015). "In addition, the diabetes-induced decreases in HK2, PKM2, and LDHA protein levels in mice testis were confirmed by western blot analysis." (PMID 35929593, 2022). "The accumulation of α-HB may be the result of enhanced glutathione synthesis or the nuclear translocation of LDHA resulting from oxidative stress, including ROS and elevated NADH/NAD+ ratios, both of which are frequently involved in the development of diabetes and cancer." (PMID 40881644, 2025).
lymph node metastasis (10 papers, 2014 to 2025). "In this study, we identified 4 coding genes associated with overall survival in LUAD patients with lymph node metastasis, namely, LDHA, ABAT, FAM117A and INPP5J, in the training set." (PMID 31015800, 2019). "Moreover, LDHA protein expression was strongly associated with pathological parameters, including lymph node metastasis and distant metastases to the lung and liver, which are common in advanced CRC." (PMID 41368023, 2025). "Patients with high LDHA expression have a poor prognosis, which is closely connected with metastasis, and high LDHA levels have been demonstrated to be related to lymph node metastasis." (PMID 37853445, 2023). "Poor prognosis is closely related to metastasis, and the high LDHA level has been shown to be correlated with lymph node metastasis." (PMID 33795650, 2021). "Moreover, high circ-CNST/LDHA/PDK1 or low miR-578 might predict shorter overall survival, advanced TNM stages, and lymph node metastasis." (PMID 33962616, 2021). "Moreover, LDHA expression levels were significantly higher in patients with lymph node metastasis (N1 group) than those without lymph node metastasis (N0 group) (p < 0.001)." (PMID 33795650, 2021).
metastatic tumors (10 papers, 2013 to 2025). "Furthermore, considering the low concordance in BRAF mutation status between primary and metastatic tumors, we further analyzed the correlation between LDHA expression and BRAF status of COAD patients." (PMID 34307169, 2021). "Previous studies discussed additional key factors that led to the stabilization and increased expression of HIF1α in primary and metastatic tumors, such as midkine or LDHA." (PMID 40806669, 2025). "We find that in metastatic tumors, both LDHA and LDHB produce lactate, while in primary tumors, both LDHA and LDHB use lactate as a substrate to produce pyruvate." (PMID 36894939, 2023). "We identified an inverse correlation between miR-34a and LDHA between primary and metastatic ccRCC, indicating that miR34a down-regulation in metastatic disease can release its inhibitory effect on LDHA with subsequent up-regulation." (PMID 24885701, 2014). "Additionally, we found a significant correlation between the expression of LDHA and the pathological stage of patients, and its expression level was higher in metastatic tumors than in primary tumors, such as in BRCA, COAD, KIRC, LUAD, PAAD, and PRAD." (PMID 38709280, 2024). "Enhanced LDHA expression has been related to tumour aggressiveness (i.e. promoting angiogenesis, immune evasion, extracellular matrix degradation, and tumour cell migration) as well as metastatic disease, and has therefore been proposed as a potential promising prognostic biomarker for cancers." (PMID 40017054, 2025). "We also find a negative partial correlation between normalized levels of LDHA and LDHB with lactate in primary tumors and a positive partial correlation between them in metastatic tumors." (PMID 36894939, 2023). "This indicates that LDHA and LDHB may operate in their non-preferential direction, to control the production of lactate in metastatic tumors and its breakdown in primary tumors." (PMID 36894939, 2023).
osteoarthritis (10 papers, 2020 to 2025). A noninflammatory degenerative joint disease occurring chiefly in older persons, characterized by degeneration of the articular cartilage, hypertrophy of bone at the margins and changes in the synovial membrane. "LDHA-mediated ROS generation in chondrocytes is now thought to be a pathogenic factor of osteoarthritis, where inhibiting LDHA with FX-11 is efficacious in articular chondrocytes." (PMID 36407005, 2022). "In osteoarthritis, sustained elevation of IL-1β level shifts the metabolism of BM chondrocytes to increase glycolysis and, in turn, promote lactate dehydrogenase A (LDHA)-mediated ROS generation." (PMID 35163048, 2022). "In addition, the intra-articular administration of oxamate, acting as an LDHA inhibitor, in a murine osteoarthritis model demonstrated reduced pain and inflammation, alongside an improvement in metabolic reprogramming." (PMID 38540033, 2024).
papillary thyroid carcinoma (10 papers, 2015 to 2025). "LDHA promotes papillary thyroid carcinoma metastasis by regulating EMT gene transcription." (PMID 37091782, 2023). "LDHA was overexpressed in follicular and papillary thyroid cancer as compared to goiter." (PMID 25880801, 2015). "However, the regulatory mechanism of LDHA inhibition and the physiological significance of the LDHA inhibitors in papillary thyroid cancer (PTC) are unknown." (PMID 34404767, 2021). "For instance, inhibiting lactate dehydrogenase A (LDHA) activates autophagy via AMPK signalling, which has anti-cancer effects in papillary thyroid carcinoma." (PMID 35459137, 2022). "Using western blot and SYBR Green Real time PCR we investigated 77 thyroid tissues including 19 goiter tissues, 11 follicular adenomas, 16 follicular carcinomas, 15 papillary thyroid carcinomas, and 16 undifferentiated thyroid carcinomas for total expression of PKM2, LDHA and FGFR1." (PMID 25880801, 2015).
COVID-19 (9 papers, 2021 to 2023). A disease caused by infection with severe acute respiratory syndrome coronavirus 2. "Among them, LDHA is related to glycolysis, and there is evidence that the expression of LDHA is significantly elevated in patients with severe COVID-19 symptoms." (PMID 36157452, 2022). "A total of 6 hub genes were obtained, including: LDHA, TRPA1, PKP2, FBN2, ERO1A, FSCN1, all of which are risk factors for LUAD/COVID-19." (PMID 36157452, 2022). "As a result, severe COVID-19 is characterized by profound lung damage, resulting in decreased blood oxygen saturation (hypoxia), as well as increased serum lactate dehydrogenase (LDHA) level." (PMID 37029220, 2023). "We identified 230 LUAD/COVID-19 DEGs and constructed a risk score containing 7 genes (BTK, CCL20, FURIN, LDHA, TRPA1, ZIC5, and SDK1) that could classify LUAD patients into two risk groups." (PMID 35733175, 2022). "In module 2, mono-CD14+ cells in patients with severe COVID-19 exhibited higher expression levels of glycolysis-related genes (LDHA and PKM) and PPP-related genes (PGD and TKT), which may be involved in the proinflammatory response (upregulation of S100A8, S100A9, S100A12, and IL1B)." (PMID 33936072, 2021). "In this regard, based on the experience of lactate dehydrogenase A (LDHA) inhibitors as anticancer therapeutics, these agents were proposed as therapy for COVID-19, because they can affect SARS-CoV-2 replication by reducing glycolysis." (PMID 36902351, 2023). "Consistent with increased glut-1 expression, upregulation of anaerobic glycolytic metabolism involving genes (LDHA, TPi, PGAM1, ALDOA) were identified in severe COVID-19 NKTs." (PMID 37029220, 2023). "Consistent with the transcription analysis, several proteins (e.g., LDHA, ADAMTSL4) related to positive regulation of apoptotic processes were preferentially present in critical COVID-19 patients." (PMID 34315889, 2021). "The analyses of these 7 gene expression levels between different clinical features suggested that BTK, SDK1, CCL20, LDHA, and ZIC5 may serve as effective biomarkers for screening and characterizing patients with LUAD/COVID-19 at different stages." (PMID 35733175, 2022). "In CD14+ monocytes, HIF-1 signaling may regulate LDHA, ALDOA, TIMP1, ELOB and IFNGR2, and PPAR signaling may regulate UBC, RXRA, DBI and ACSL1 in COVID-19 patients." (PMID 33936072, 2021).
Hyperglycemia (9 papers, 2018 to 2026). An increased concentration of glucose in the blood. "In control cells, we recognized an increase in glucose uptake, a raise of hexokinase and pyruvate dehydrogenase activity, and LDHA protein accumulation under hyperglycemia." (PMID 35328751, 2022). "Furthermore, our findings demonstrate that the LDHA isoform is responsible for low LDH activity in hyperglycemia." (PMID 40269097, 2025). "Additionally, we observed in 1BR.3.N WWOX OE cell line variant the reduction of PKM2 and LDHA protein expression in normoxia normoglycemia, the decrease of HK2 protein in normoxia hyperglycemia, and PKM2 reduction in hypoxia hyperglycemia condition relative to 1BR.3.N WT cell line variant." (PMID 35328751, 2022).
Obesity (9 papers, 2015 to 2026). Accumulation of substantial excess body fat. "HIF-1 signaling, induced by hypoxic adipose environments in obesity, upregulates glycolytic enzymes (e.g., LDHA) and angiogenic factors (e.g., VEGF), contributing to adipocyte hypertrophy and fibrosis." (PMID 40625623, 2025). "Rats were protected from obesity-related glucose intolerance and insulin resistance by adipocyte-selective deleting of the enzyme lactate dehydrogenase A (LDH-A), which converts pyruvate to lactate." (PMID 37516743, 2023). "Lactate production is highly increased during obesity, while hypothalamic LDHA is regulated by leptin signaling in obese rats." (PMID 36407005, 2022). "Exposure of human granulosa cell line (HGrC1) to FF from women with PCOS and obesity was associated with a marked reduction in glycolytic capacity (p < 0.05) and decreased mRNA expression of key glycolytic regulators, including GLUT1, HK2 and LDHA (p < 0.05)." (PMID 41847445, 2026). "Alongside transcriptional mitochondrial oxidative downregulation, we observed higher pyruvate levels in acquired obesity, accompanied by higher glycolytic phosphofructokinases (PFKM and PFKP) and LDHA protein levels." (PMID 33948567, 2021). "A panel of hypoxia-regulated genes (VEGF, ADM, LDHA, SLC2A1) showed consistently higher mean values in the endometrium of women with obesity and in uteri of mice with increased weight vs normal controls, although statistical significance was not reached." (PMID 33836495, 2021). "These enzymes were glucose 6-phosphate isomerase (GPI), triosephosphate isomerase (TPI), enolase (Eno3), lactate dehydrogenase (LDHa), glyoxalase-1 (Glo1) and the mitochondrial DLD, whose expressions were modified by AM251 in hypercaloric diet-induced obesity." (PMID 26671069, 2015). "Cross-examination of benign and malignant tumor tissue biopsies revealed a significant shift in LDH isozyme expression towards the “muscle-type” LDH with corresponding changes in protein expression of LDHA (increased) and LDHB (decreased) in malignant tumor tissue, regardless of obesity." (PMID 33353120, 2020).
pulmonary fibrosis (9 papers, 2018 to 2024). Chronic progressive interstitial lung disorder characterized by the replacement of the lung tissue by connective tissue, leading to progressive dyspnea, respiratory failure, or right heart failure. "GPEG-140, an inhibitor of LDHA, reduces lactate production and histone lactylation, exerting anti-pulmonary fibrosis effects." (PMID 39683818, 2024). "These research findings suggested that targeting the LDHA-mediated pathway offered a novel approach to combat pulmonary fibrosis and halt disease progression." (PMID 38773615, 2024). "Because IMR‐90 fibroblasts are derived from fetal lungs and aging contributes to the development of lung fibrosis, we next examined LDHA and LDHB expression in age‐matched control and IPF fibroblasts under normoxic and hypoxic conditions." (PMID 37653539, 2023). "Studies have shown that the LDHA inhibitor gossypol inhibited ionizing radiation and bleomycin-induced pulmonary fibrosis." (PMID 35328434, 2022). "Increased levels of LDHA and its metabolic product, lactate, were found in patients with idiopathic pulmonary fibrosis (IPF)." (PMID 34576239, 2021). "We analyzed the expression of LDHA in the mouse pulmonary fibrosis model established by silica and found that the positive expression of LDHA was significantly enhanced in the model group." (PMID 34576239, 2021). "In our manuscript, we highlight the potential of LDHA inhibitors as a therapy for pulmonary fibrosis." (PMID 29795645, 2018). "Xie et. al. reported that inhibition of 6-phosphofructo-2-kinase/fructose-2,6-biphosphatase 3 (PFKFB3), a glycolytic enzyme that is upstream of LDHA, also inhibits bleomycin-induced pulmonary fibrosis." (PMID 29795645, 2018). "Our lab has previously identified the enzyme lactate dehydrogenase-A (LDHA) as a potential therapeutic target in pulmonary fibrosis." (PMID 29795645, 2018). "We have also demonstrated that the enzyme responsible for the production of lactic acid, lactate dehydrogenase-A (LDHA), is elevated in lung tissue isolated from patients with idiopathic pulmonary fibrosis (IPF)." (PMID 29795645, 2018). "Nonetheless, LDHA inhibitors have therapeutic potential and represent a promising novel target for pulmonary fibrosis." (PMID 29795645, 2018). "We found increases in LDHA protein and its metabolic product, lactate, in patients with idiopathic pulmonary fibrosis (IPF)." (PMID 29795645, 2018). "We wanted to examine whether there was a link between lung tissue metabolic changes and matrix and tissue stiffness changes in pulmonary fibrosis by interrogating LDHA and other metabolic pathways in the TG2 KO mice." (PMID 38959068, 2024). "Collectively, our in vitro and IHC results consistently suggest that the alteration of LDHA/LDHB and GPR‐81 is associated with the fibrotic process and may contribute to the development and progression of lung fibrosis." (PMID 37653539, 2023). "Here we hypothesized that the increase in LDHA expression in vivo subsequently induces the development of pulmonary fibrosis." (PMID 29795645, 2018). "Our results demonstrate that inhibition of LDHA with the inhibitor gossypol is effective at both preventing and treating bleomycin-induced pulmonary fibrosis, and suggests that LDHA may be a potential therapeutic target for pulmonary fibrosis." (PMID 29795645, 2018). "To determine whether the occurrence and development of experimental pulmonary fibrosis induced by silica are related to glycolysis reprogramming, we performed immunohistochemistry (IHC) staining of LDHA in the lung tissues of the control group and the model group." (PMID 34576239, 2021). "The established role of extracellular pH and its ability to activate latent TGF-β1 along with the observation of similar effects of gossypol in vitro and in vivo are all consistent with the hypothesis that LDHA inhibition is the primary mechanism by which gossypol inhibits pulmonary fibrosis." (PMID 29795645, 2018).
pulmonary fibrosis (continued). "It was shown that lactate-dehydrogenase-A (LDH-A), the enzyme which produces lactate, is overexpressed in UIP, and a decrease in extracellular pH induces a rise in TGF-β, a known mediator of pulmonary fibrosis." (PMID 32851507, 2021). "Our data build on previous data in support of the role of LDHA inhibition in the prevention and reversal of TGF-β1 induced myofibroblast differentiation and the subsequent development of pulmonary fibrosis." (PMID 29795645, 2018). "LDHA expression and LDH activity are increased in fibrotic murine lungs following bleomycin, and inhibition of pyruvate generation with a phosphofructokinase 3B inhibitor or broad‐spectrum LDH inhibition diminished lung fibrosis in that model." (PMID 37653539, 2023). "Here we hypothesize that pharmacologic inhibition of LDHA via the LDH inhibitor, gossypol, will abrogate fibrotic changes in an in vivo model of bleomycin-induced pulmonary fibrosis." (PMID 29795645, 2018).
acute myeloid leukemia (8 papers, 2019 to 2025). Acute myeloid leukemia (AML) is a group of neoplasms arising from precursor cells committed to the myeloid cell-line differentiation. "H4K5la promoted PD-L1 expression and drive immunosuppression in acute myeloid leukemia, whereas H4K12la activated the transcription of HIF1A, PKM, and LDHA, thereby promoting glycolysis and forming a positive feedback glycolysis/H4K12la/PKM2 loop in microglia." (PMID 40784455, 2025). "The M2 phenotype of regulated glycolytic enzyme pyruvate kinase (PKM2) and lactate dehydrogenase A (LDHA), another downstream component of an aerobic glycolytic pathway were found to be over-expressed and have shown a profound effect on acute myeloid leukemia (AML) and CML." (PMID 31506393, 2019). "Nevertheless, increased levels of lactate and LDHA have been frequently reported as markers of poor prognosis in different types of leukemia such as acute lymphoblastic leukemia (ALL), acute myeloid leukemia (AML), chronic lymphoblastic leukemia (CLL) and chronic myeloid leukemia (CML)." (PMID 36330529, 2022).
cholangiocarcinoma (8 papers, 2014 to 2024). A carcinoma that arises from the intrahepatic biliary tree (intrahepatic cholangiocarcinoma) or from the junction, or adjacent to the junction, of the right and left hepatic ducts (hilar cholangiocarcinoma). "Since tumor cells robustly convert pyruvate into lactate, one would expect a high expression of LDHA in cancer cells as well as cholangiocarcinoma (CCA)." (PMID 30866966, 2019). "In cholangiocarcinoma, LDHA silencing promoted apoptosis through miR-30d-5p/LDHA axis." (PMID 35155437, 2022).